FTO (FTO alpha-ketoglutarate dependent dioxygenase)
Diseases named in the same sentence as FTO in open-access papers (continued):
Sharing a sentence is not in itself a finding about the gene and the disease.
fibrosis (4 papers, 2016 to 2025). the formation of excess fibrous connective tissue in an organ or tissue in a reparative or reactive process. "EPRS was required for cardiac fibrosis induced by FTO silencing." (PMID 39538146, 2024). "Besides, m6A modification was found to be significantly enhanced in failed mammalian hearts, accompanied by decreased alpha-ketoglutarate dependent dioxygenase (FTO) myocardial contractile dysfunction, while overexpression of FTO reduced myocardial fibrosis and increased angiogenesis." (PMID 37193033, 2023). "EPRS, negatively affected by FTO via IGF2BP3-mediated m6A modification, was critical in regulating cardiac fibrosis after MI." (PMID 39538146, 2024).
Hepatitis (4 papers, 2018 to 2025). Inflammation of the liver. "Genetic studies revealed higher prevalence of hepatitis in individuals homozygous for the rs9939609A variant of the FTO gene compared with other patients (p = 0.03)." (PMID 30111348, 2018). "Genetic studies revealed higher prevalence of hepatitis in patients homozygous for the rs9939609A variant of the FTO gene compared with other patients (p = 0.03)." (PMID 30111348, 2018). "Higher prevalence of hepatitis in individuals homozygous for the rs9939609A variant of the FTO gene might be associated with prolonged impairment of liver function thus causing higher susceptibility to infections." (PMID 30111348, 2018). "The study revealed higher prevalence of hepatitis in patients treated with CRT (p = 0.0001) and in patients homozygous for the rs9939609A variant of the FTO gene (which in our previous study was associated with higher BMI) compared with other patients." (PMID 30111348, 2018). "In contrast, other m6A regulators, including METTL3, METTL14, WTAP, FTO, ALKBH5, YTHDC1, and YTHDC2, exhibited different protein expression patterns during ConA-induced hepatitis." (PMID 40092485, 2025). "However, clinical characteristics such as age, hepatitis history, AFP, liver cirrhosis, multiple tumors, tumor encapsulation, and TNM stage were not directly linked to FTO expression." (PMID 40316995, 2025).
injury (4 papers, 2020 to 2022). Damage inflicted on the body as the direct or indirect result of an external force, with or without disruption of structural continuity. "Blocking this increase can reverse m6A loss caused by nerve injury and reduce nerve injury-related hyperalgesia, suggesting that FTO participates in the peripheral mechanism of NP in an RNA m6A-dependent manner." (PMID 35634463, 2022). "Increased FTO may maintain the nerve trauma-induced increase in G9a expression and consequent downregulation of G9a-determined MOR in nerve trauma-related DRG neurons." (PMID 34803588, 2021). "Although FTO has the potential expression in DRG immune cells (e.g., NK cells and monocytes) and played an active role in nerve degeneration after nerve injury, morphologic observation of the FTO‐labeled DRG cells does not support this expectation." (PMID 32670741, 2020).
leukopenia (4 papers, 2018 to 2022). "The variant diminishes FTO activity and predisposes individuals harboring the variant to thiopurine-induced leukopenia." (PMID 30349479, 2018). "In Asian population, the polymorphism c.400G > A of the alpha-ketoglutarate-dependent dioxygenase gene (FTO) was associated with a 65% decrease in its enzymatic activity and an increased likelihood of leukopenia." (PMID 35448412, 2022).
liver disease (4 papers, 2014 to 2025). "This suggests an association of FTO genetic variation with ALT might be mediated through NAFLD, though participants with overt liver disease were excluded from our study." (PMID 28915859, 2017). "Further, expression of the m6A METTL3 writing complex, erasers (demethylases: FTO and ALKBH5), and m6A readers (RBPs) are altered in human NAFLD and in experimental models of liver disease and contribute to NAFLD, HCC, and CCA." (PMID 37628704, 2023).
mood disorder (4 papers, 2021 to 2025). A cognitive disorder a disturbance in which the person's mood is hypothesized to be the main underlying feature. "Recent studies have identified genetic variants linked to both mood disorders and cardiometabolic conditions, including CACNA1D, FTO, BDNF, POMC, IGF." (PMID 39834212, 2025). "Mood disorders, body mass composition by using bioelectrical impedance analysis (BIA) and FTO gene polymorphisms (rs9939609, rs1558902) by tetra-primer amplification refractory mutation system PCR (T-ARMS-PCR) were assessed." (PMID 38540130, 2024). "In light of the established fact that mood disorders (such as MDD) have a higher incidence in women, therefore further work investigating the role of FTO in female mice may help elucidate potential sex-specific mechanisms underlying mood disorders." (PMID 34836959, 2021).
neuroblastoma (4 papers, 2021 to 2025). Neuroblastoma (NB) is the most common solid, extracranial childhood tumor. "Our earlier studies with FTO knockdown using neuroblastoma cells indicated that FTO downregulation altered metabolic functions through activation of downstream metabolic mediators including AMPk." (PMID 40722726, 2025). "Application of imipramine or amitriptyline, which are tricyclic antidepressants (TCAs), increased the expression of FTO, whereas fluoxetine, which is a selective serotonin reuptake inhibitor (SSRIs), decreased FTO in mouse neuroblastoma 2A cells." (PMID 37047192, 2023). "Li and coworkers have shown that an increased FTO expression delays forskolin-mediated dephosphorylation of one of CaMKII’s cellular targets: cAMP response element-binding protein (CREB) in human neuroblastoma cells." (PMID 34639211, 2021). "For example, the interaction between FTO and CaMKII isoforms decreased the level of cAMP response element-binding protein (CREB) phosphorylation in human neuroblastoma cells (SK-N-SH)." (PMID 34639211, 2021).
prediabetes (4 papers, 2012 to 2023). "In summary, we found significant associations between prediabetes risk and five variants closely related to the FTO, HNF4A, WFS1, DUSP9, and ZFAND6 genes (rs4812829, rs1801214, rs5945326, rs11642841, and rs11634397) among Saudi Arabian adults." (PMID 36980809, 2023). "Prediabetes risk increased by 57% among participants with the homozygous AA genotype of rs11642841 (FTO) compared to the CC genotype (p = 0.02)." (PMID 36980809, 2023). "Therefore, the study was designed to investigate both genetic (TCF7L2-rs7903146, IRS1-rs1801278, INSR-rs3745551, CDKN2A-rs10811661, and FTO-rs9939609) and environmental factors for prediabetes in a Vietnamese population." (PMID 26334876, 2015). "This cross-sectional study aimed to investigate the independent risk factors for prediabetes, considering the contribution of genetic factors (TCF7L2-rs7903146, IRS1-rs1801278, INSR-rs3745551, CDKN2A-rs10811661, and FTO-rs9939609), socio-economic status, and lifestyle factors." (PMID 26334876, 2015).
Premature ovarian insufficiency (4 papers, 2020 to 2022). Amenorrhea due to loss of ovarian function before the age of 40. "A previous study has demonstrated that compared to the control group, the expression level of FTO in premature ovarian insufficiency (POI) patients and mouse models was significantly lower." (PMID 35219326, 2022). "The reduction of FTO protein expression was concomitant with elevated m6A level in ovarian tissue of premature ovarian insufficiency patients." (PMID 33511112, 2020). "Remarkably, a previous study reported that a decrease in FTO in the GCs of patients with premature ovarian insufficiency increased the total amount of m6A, while another study reported that alkylating agents could increase the abundance of m6A modifications in GCs." (PMID 34315853, 2021). "Furthermore, FTO was found to be involved in premature ovarian insufficiency-mediated infertility." (PMID 33511112, 2020). "Among readers of m6A methylation, studies confirmed that the protein level of FTO, but not ALKBH5, was significantly decreased in human aged ovaries and in ovaries of women diagnosed with premature ovarian insufficiency." (PMID 35346019, 2022).
renal carcinoma (4 papers, 2021 to 2024). A carcinoma arising from the epithelium of the renal parenchyma or the renal pelvis. "By contrast, low levels of the m6A erasers FTO and ALKBH5 are linked with poor renal carcinoma prognosis." (PMID 33232910, 2021).
Simpson-Golabi-Behmel syndrome (4 papers, 2011 to 2020). Simpson-Golabi-Behmel syndrome is a rare X-linked multiple congenital anomalies syndrome, characterized by pre- and postnatal overgrowth, distinctive craniofacial features, variable congenital malformations, organomegaly and an increased tumor risk. "In addition, SGBS cells carry an FTO risk allele and the cells do not have a Simpson-Golabi-Behmel syndrome typical mutation in the glypican-3-gene (GPC3) what the name of the cell strain would suggest." (PMID 32466532, 2020). "In in vitro differentiated primary human preadipocytes and in Simpson-Golabi-Behmel syndrome (SGBS) preadipocytes, FTO expression is downregulated during adipogenic differentiation." (PMID 23236435, 2012).
steatosis (4 papers, 2014 to 2023). Increased lipid within the cytoplasm of cells. "Then, a causal link between FTO and steatosis was established by in vivo FTO overexpression." (PMID 36352530, 2023). "However, the livers with FTO overexpression exhibited more prominent steatosis when compared with those of the controls." (PMID 35282837, 2022).
ulcerative colitis (4 papers, 2025). An inflammatory bowel disease involving the mucosal surface of the large intestine and rectum. "Here, we verified that FTO deficiency facilitated oral epithelia dysfunction in the context of OLP, consistent with other studies showing that FTO insufficiency aggravates ulcerative colitis." (PMID 39995976, 2025). "In ulcerative colitis, FTO downregulation exacerbates inflammation by altering sphingolipid metabolism, suggesting an m6A-dependent mechanism." (PMID 39980685, 2025). "The downregulation of FTO promotes the occurrence of ulcerative colitis (UC) by reducing the expression of CERS6 and exacerbates UC through m6A-dependent mechanisms." (PMID 40829428, 2025).
Brain atrophy (3 papers, 2019 to 2021). Partial or complete wasting (loss) of brain tissue that was once present. "As a typical example, whereas the FTO rs9939609 A variant is a risk factor for brain atrophy in old age and AD development, it appears to be neuroprotective against MDD." (PMID 34095121, 2021). "Carriers of the FTO variant rs9939609 were reported to display systematic deficits in brain volume consistent with brain atrophy in the elderly." (PMID 34095121, 2021). "The homozygous mutation of FTO gene can reduce the brain capacity of healthy elderly people, increase the susceptibility to brain atrophy during aging, and even affect the brain volume of adolescents." (PMID 31452869, 2019).
cataract (3 papers, 2022 to 2025). Partial or complete opacity of the crystalline lens of one or both eyes that decreases visual acuity and eventually results in blindness. "Interactions between the FTO SNP and protein intake were shown to increase the risk of PSC cataracts in individuals with dyslipidemia." (PMID 36572895, 2022).
cholangiocarcinoma (3 papers, 2019 to 2024). A carcinoma that arises from the intrahepatic biliary tree (intrahepatic cholangiocarcinoma) or from the junction, or adjacent to the junction, of the right and left hepatic ducts (hilar cholangiocarcinoma). "IDH1/2 mutations, one of the most characteristic gene mutations in cholangiocarcinoma, result in elevated levels of (R)-2-hydroxyglutarate (R-2HG), which inhibits the α-ketoglutarate (α-KG)-dependent dioxygenase activity of FTO." (PMID 38365891, 2024). "Furthermore, FTO and other m6A modification enzymes are also rarely mutated in cholangiocarcinoma, and their copy number changes are unknown." (PMID 31143705, 2019). "ERα mRNA m6A methylation is significantly upregulated by R-2HG due to FTO degradation, which may then result in suppressing ERα protein expression via translational regulation, hence reducing cholangiocarcinoma." (PMID 37270544, 2023). "Neither mutations nor copy number alterations in FTO or other m6A modification enzymes were found in cholangiocarcinoma." (PMID 31143705, 2019). "Despite the anti-tumor effects of FTO inhibition have shown great promise in cholangiocarcinoma, there is currently a lack of data to support its application in in vivo models and clinical settings." (PMID 38365891, 2024).
Cirrhosis (3 papers, 2019 to 2026). A chronic disorder of the liver in which liver tissue becomes scarred and is partially replaced by regenerative nodules and fibrotic tissue resulting in loss of liver function. "FTO was distributed in all cell populations and was highly expressed in NAFLD tissues at different pathological stages, especially in NASH with cirrhosis and in the end‐stage state, which again demonstrated that the FTO gene plays an important role in the pathogenesis of NAFLD." (PMID 40552337, 2025).
cutaneous melanoma (3 papers, 2021 to 2024). A primary melanoma arising from atypical melanocytes in the skin. "Interestingly, in addition to somatic FTO changes similarly shown to play a role in cutaneous melanomagenesis, recent genome-wide association studies have implicated germline FTO polymorphisms in genetic susceptibility to develop cutaneous melanoma." (PMID 39518125, 2024). "Recent studies have shown remarkable progress in linking m6A RNA demethylation with fat mass and obesity-associated protein (FTO) and ALKBH5, which is strongly associated with cutaneous melanoma development and reactions to cancer therapy." (PMID 34291082, 2021).
gynecological cancer (3 papers, 2023 to 2024). "This analysis underscores the growing relevance of investigations into the FTO gene in elucidating the mechanisms underlying gynecological cancers and exploring potential therapeutic avenues." (PMID 39175477, 2024). "All of these studies demonstrated the critical role of RNA demethylases in cancer development, and the targeted inhibition of FTO showed beneficial effects in many types of neoplasms, including gynecological cancer." (PMID 37175660, 2023). "So far, increasing evidence demonstrates that FTO plays an oncogenic role in gynecological cancer, including cervical and ovarian cancer." (PMID 37175660, 2023). "Abnormal expression of FTO and ALKBH5 is closely associated with the occurrence of various diseases, such as leukemia, infertility, and obesity, bladder cancer, etc. m6A demethylase also plays an important role in gynecological cancers." (PMID 38343637, 2024). "Current research efforts are exploring the role of FTO in the development of gynecological cancers." (PMID 39175477, 2024). "However, the precise mechanisms by which FTO influences the development of gynecological cancers remain largely unknown." (PMID 39175477, 2024). "Therefore, targeted inhibition of FTO may provide a promising option for treating patients with gynecological cancer." (PMID 37175660, 2023). "All these reports indicate that the function of FTO and ALKBH5 in gynecologic cancer mainly depends on the demethylation of m6A, and they play an important role in the occurrence and development of gynecologic cancer." (PMID 38343637, 2024).
head and neck cancer (3 papers, 2021). A primary or metastatic malignant neoplasm affecting the head and neck. "Interestingly, FTO level is highly elevated in head and neck cancer and correlates with tumor development." (PMID 33925955, 2021). "We have already shown that overexpression of the FTO protein occurs in head and neck cancer (HNSCC) and that FTO level was positively correlated with the tumor size, indicating the involvement of this protein in cancer metabolism." (PMID 34639211, 2021). "Further, our analysis of protein lysates from head and neck cancer (HNSCC), with the use of size exclusion chromatography indicated that FTO was located in a wide spectrum of molecular fractions—from several tens to several hundred kDa." (PMID 34639211, 2021). "It was found that head and neck cancer samples with high expression of writer genes KIAA1429 were in positive correlation with eraser genes ALKBH3 and FTO, while tumors with a high expression of writer genes (RBM15, RBM15B, and CBLL1) exhibited a low expression of eraser genes (ALKBH3 and FTO)." (PMID 35198565, 2021).
Impaired glucose tolerance (3 papers, 2011 to 2017). An abnormal resistance to glucose, i.e., a reduction in the ability to maintain glucose levels in the blood stream within normal limits following oral or intravenous administration of glucose. "In the DPS, in men with Impaired Glucose Tolerance the AA genotype of rs9939609 in FTO was associated with 2.09-fold risk of CVD in men." (PMID 28133617, 2017).
inflammatory bowel disease (3 papers, 2022 to 2025). A spectrum of small and large bowel inflammatory diseases of unknown etiology. "FTO inhibitors may represent a potential function to alleviate the pathological changes of chronic inflammation imprints and immune disorders in CoSCs, maintaining their pluripotency and differentiation balance under inflammatory bowel disease." (PMID 39872548, 2023). "Inflammatory bowel disease (IBD) exhibits paradoxical m6A regulatory dynamics: METTL3 and FTO demonstrate elevated expression concomitant with METTL14 and HuR downregulation." (PMID 40963968, 2025).
keloid (3 papers, 2022 to 2025). An irregularly shaped, elevated mark on the skin caused by deposits of excessive amounts of collagen during wound healing. "The total m6A levels of keloids were decreased, and the overexpression of FTO in human fibroblasts enhanced cell migration." (PMID 40860194, 2025). "Nevertheless, the FTO overexpression could be inhibited by glucocorticoids, and this provided a potential mechanism of glucocorticoid treatment in keloids via m6A-related pathways." (PMID 40860194, 2025). "Then they constructed a keloid diagnostic Lasso model based on 5 genes and divided keloid samples into high-risk and low-risk groups, showing that m6A regulators ALKBH5, FTO, and HNRNPA2B1 were upregulated in the high-risk group, while YTHDF2 was downregulated." (PMID 40860194, 2025). "This highlighted the significance of FTO in keloid development, suggesting that targeting FTO-mediated m6A demethylation could offer a new therapeutic approach for keloid treatment." (PMID 39472463, 2024). "Among all m6A regulators, the levels of METTL3 and WTAP were significantly higher in keloid samples, while the levels of ALKBH5, FTO, and METTL14 exhibited little differences." (PMID 40860194, 2025). "But there is no significant change in METTL14, FTO, and ALKBH5 between these two groups (data are not shown), which indicates that the keloid is under a hypermethylated condition." (PMID 36263010, 2022).
left ventricular hypertrophy (3 papers, 2015 to 2025). Enlargement of the LEFT VENTRICLE of the heart. "The homozygous mutations in FTO lead to left ventricular hypertrophy, which supported that FTO played an important role in early development of cardiovascular systems." (PMID 40606020, 2025). "Our previous work has also shown that the expression of FTO can be increased by cinnamic acid in cardiomyocytes, which in part accounts for cinnamic acid-conferred protection against pressure overload-induced left ventricular hypertrophy." (PMID 40771928, 2025). "Based on these findings, an impact of FTO SNPs on CX43 may be suggested which goes beyond the altered expression of CX43 found in left ventricular hypertrophy in AVS patients." (PMID 26431034, 2015).